MIR154 (microRNA 154)
Synonyms: hsa-mir-154; MIRN154; mir-154
Gene: MicroRNA gene on chromosome 14 (101,059,755 to 101,059,838, forward strand). Ensembl gene ENSG00000207978.
Gene Ontology:
Biological process: miRNA-mediated post-transcriptional gene silencing
Cellular component: RISC complex
Homologues: Orthologues: chimpanzee ptr-mir-154 (100% identical), rat Mir154 (94% identical), macaque mml-mir-154 (88% identical), mouse Mir154 (77% identical), guinea pig MIR154 (73% identical). Paralogues in human: MIR494 (75% identical), MIR487A (70% identical), MIR323A (69% identical), MIR539 (69% identical), MIR382 (68% identical), MIR323B (65% identical), MIR1185-1 (63% identical), MIR410 (63% identical), MIR487B (63% identical), MIR1185-2 (61% identical), MIR496 (60% identical), MIR369 (57% identical), and 4 more.
Diseases named in the same sentence as MIR154 in open-access papers:
MIR154 is named in the same sentence as 2 diseases in open-access papers, as found by Europe PMC text mining. Sharing a sentence is not in itself a finding about the gene and the disease. The quoted sentences say what the papers report.
lung carcinoma (1 paper, 2019). "This analysis revealed that SNP rs1700 overlapped with the predicted binding site for MIR154, which is known to promote myocardial fibrosis (Dong, Liu, & Wang, 2018) and regulating the metastatic behavior of nonsmall lung cancer cells." (PMID 30722102, 2019).
MIR154 also shares sentences with these, for which no sentence is quoted: Myocardial fibrosis (1 paper).